MMP2 (matrix metallopeptidase 2)
Diseases named in the same sentence as MMP2 in open-access papers (continued):
Sharing a sentence is not in itself a finding about the gene and the disease.
breast cancer (continued). "Analogously, upregulated SCUBE2 in breast cancer primary tumor cells can be proteolytically cleaved by matrix metalloproteinase 2 (MMP-2) to separate the C-terminal CR and CUB domains from the N-terminal EGF-like repeats and the spacer region." (PMID 37237303, 2023). "Matrine inhibited breast cancer cell migration by reducing the activation of MMP9/MMP2, P65, VEGFR1 and epidermal growth factor (EGF)." (PMID 36706149, 2023). "MMP-2 and MMP-9 play an important role in metastasis and have been linked to lymph node metastasis in breast cancer cell lines as well as to poor response to chemotherapy in osteosarcoma." (PMID 36674555, 2023). "It is possible that the TMBIM6-induced progression and metastasis of breast cancer can be mediated through MMP-2 and/or MMP-9." (PMID 37057283, 2023). "For instance, extracellular HSP70 and HSP90 are critical to interact with MMP2 and enhance migration in breast cancer." (PMID 36906534, 2023). "This hypoxia-induced glycolysis promotes lactate secretion, enhancing the activation of TGFβ1/p38 mitogen-activated protein kinase/matrix metalloproteinase 2/9 (MAPK/MMP2/9) signaling in breast cancer cells, promoting the invasiveness of tumor cells." (PMID 37168385, 2023). "MMP-2 levels in circulating blood have been considered as a breast cancer metastasis marker and are related to mortality rates." (PMID 36936170, 2023). "Overexpression of MMP-2 and MMP-9 was linked to poor prognosis in oral cancer, lung cancer, breast cancer, retinoblastoma, bladder cancer, and ovarian epithelial cancer." (PMID 38069361, 2023). "Diltiazem administration in vivo also upregulates serum level of GDF-15, diminishes EMT and MMP-9/MMP-2 expression, leading to the decrease of lung metastasis of breast cancer." (PMID 35963873, 2022). "Another in vitro study showed that PAR2-induced MMP-2 expression promotes the migration of human breast cancer cells through the p38 MAPK/MK2/HSP27 axis." (PMID 36741729, 2022). "Formononetin, a natural drug and the active component of the herb Astragalus membranaceus, can inhibit the migration and invasion of breast cancer cells by inhibiting MMP-2, MMP9, and PI3K/AKT signaling pathways." (PMID 35463082, 2022). "For example, upregulated expression of TPX2 enhances breast cancer metastasis by mediating MMP2 and MMP9 expression." (PMID 36225568, 2022). "Recent studies have confirmed that REA nanoparticles inhibit tumor cell migration, invasion by inhibiting matrix metalloproteinase-2 (MMP-2), 9 expressions, and angiogenesis in mouse breast cancer transplant tumors." (PMID 36133791, 2022). "In this work, Epi-Nio-HA successfully reduced the migration of 4T1 and SkBr3 breast cancer cell lines by downregulating the expressions of MMP-2 and MMP-9." (PMID 35875198, 2022). "For instance, Massaque and colleagues identified 18 genes, including IL13Ra2, SPARC, MMP1, and MMP2, which can lead to breast cancer metastasis to the lungs." (PMID 35045088, 2022). "Recent studies have shown that HDAC2 was essential for increasing breast cancer cell motility through the induction of the breast cancer metastasis markers MMP2 and N-cadherin." (PMID 35743249, 2022). "We aimed to evaluate the contribution and association of single-nucleotide polymorphisms (SNPs) in MMP genes (MMP1, MMP2, MMP3, MMP7, MMP8, MMP9) with clinicopathological breast-cancer features." (PMID 36009438, 2022). "Statins also block the adhesion, migration and invasion of breast cancer cells by reducing integrin-binding activity and MMP2 and MMP9 activity." (PMID 36139556, 2022). "SD-7300, an oral inhibitor of MMP-2, -9, and -13, has shown promising preclinical therapeutic effects for breast cancer." (PMID 36479070, 2022). "Secreted Hsp90 promoted tumor cell invasiveness in a breast cancer model in an MMP2-dependent manner." (PMID 36060252, 2022).
breast cancer (continued). "MMP2 is highly expressed in numerous cancers including breast cancer, cervical cancer, bladder cancer, gastric cancer, and lung cancer, which makes MMP2 an important anticancer therapy target." (PMID 36624735, 2022). "On the other hand, host-derived MMP-2, which is mainly produced from stromal fibroblasts, was also shown to promote the outgrowth of mammary tumors in the lungs in vivo." (PMID 36741729, 2022). "In detail, the NF-kB pathway activated by Notch signaling increased MMP-2 and MMP-9 genes, leading to the activation of urokinase PA (uPA), a plasminogen activator, which causes severe symptoms or death in breast cancer." (PMID 35743249, 2022). "MMP-1 was reported to be upregulated in Adriamycin MCF-7 breast cancer cells, along with MMP-2 and MMP-9." (PMID 35586209, 2022). "Qiong and Yin revealed that epirubicin resistance in breast cancer was promoted by an elevated level of orosmucoid 1, which was induced by MMP-2 and MMP-9 upregulation." (PMID 35586209, 2022). "In highly invasive CD44 expressing breast carcinomas, tumor cells also activate MMP-2 and MMP-9 resulting in degradation of collagen type IV in vascular basement membranes." (PMID 36497364, 2022). "SPP1-R3 aptamer was used to inactivate SPP1 and disturb surface binding of SPP1 to its cell surface CD44 receptor and mediators of ECM degradation, MMP-2, in human breast cancer cells." (PMID 34676217, 2021). "Treatment with sHA, however, lead to the downregulation of MT1-MMP, known to be involved in breast cancer cell migration and invasion, as well as the downregulation of MMP2 and MMP9, two MMPs with pivotal role in ECM degradation." (PMID 34944559, 2021). "For instance, BMP‐stimulated MMP‐2 and ‐9 activity was shown to be a relevant mechanism in breast cancer cell migration and invasion." (PMID 33629769, 2021). "In particular, MMP-2/9 overexpression has been reported to be a poor prognostic factor for breast cancer." (PMID 34006286, 2021). "As a result, STAT3 upregulated the expression of breast cancer-aggravating genes, such as CCND1 and MMP2, thereby enhancing the proliferation and migration of breast cancer cells." (PMID 34335938, 2021). "Among the MMPs, MMP-2 and MMP-9 are strongly correlated with tumor invasion and metastasis in breast cancers, as MMP-2 is more constitutively expressed in metastatic cancers and MMP-9 is highly inducible by various stimuli." (PMID 34483918, 2021). "It was suggested that the statin inhibited invasion and metastasis in the aggressive breast cancer cell line via blockage of the mevalonate pathway and inhibition of both MMP-2 and MMP-9." (PMID 33906301, 2021). "In breast cancer the extracellular hsp70 and heat shock protein 90 alpha were identified and shown to activate MMP-2 to facilitate cell migration and invasion." (PMID 33732640, 2021). "In breast cancer, MMP2 and MMP9 were determined as important downstream effectors of PI3K/AKT signaling and MMP2 was shown to be activated by PI3K/AKT, regulated by RICTOR for the vasculogenic mimicry of tumor cells." (PMID 35096817, 2021). "HSP90-loaded exosomes from metastatic breast cancer cells activate MMP2, leading to degradation of ECM molecules and release of growth factors, that boost signal transduction resulting in increased cancer cell invasion." (PMID 33809973, 2021). "Previous studies have shown that higher expression of CD147, MMP-2, and MMP-9 is associated with breast cancer progression." (PMID 34096887, 2021). "Recently, it has been reported that Myr suppresses breast cancer metastasis through the downregulation of the activity of MMP-2 and MMP-9 (MDA-Mb-231Br cells)." (PMID 33498927, 2021). "Other MMPIs focusing on malignancies and tested in clinical trials include neovastat, which strongly inhibits MMP2 activity (metastatic kidney cancer, advanced colorectal/breast cancer) and BMS-275291, a wide-spectrum MMPI (lung, breast cancer)." (PMID 33809973, 2021).
breast cancer (continued). "BB was also reported to suppress migration by targeting ephrin-B2 then decreased MMP-2/9 protein expression in breast cancer ZR-75-30 cells." (PMID 34771481, 2021). "In fact, it has been seen that extracellular HSP90 alpha in fibrosarcoma and breast cancer cells promote MMP2 activation, which is critical for tumor invasiveness." (PMID 33445445, 2021). "A previous study showed that PLAU1, MMP1, and MMP2 are involved in signaling pathways related to invasion in breast cancer." (PMID 33816223, 2021). "Expression of LTB4R was essential for CD8+ T cell infiltration into tumours and invasiveness of ovarian cancer cells and breast cancer cells was increased by MMP-2 pathways and IL-8 pathway respectively." (PMID 34229684, 2021). "λ-CO also downregulated additional factors linked with ECM remodelling and breast cancer progression, in particular MT1-MMP and its direct target MMP-2, and our data suggest that HPSE protein level acts as an orchestrator of MMP-2 activation." (PMID 34677445, 2021). "Western blot results showed that the expression of VE-cadherin, VEGFR-1, MMP-9, and MMP-2 was increased in both breast cancer cells." (PMID 34055597, 2021). "It was suggested that oleuropein inhibits the EMT process in breast cancer cells by inducing upregulation of the epithelial marker E-cadherin, and downregulation of mesenchymal markers MMP-2 and MMP-9." (PMID 34578851, 2021). "In the ER + breast cancer, Rab27b activates MMP2 secretion and stimulates breast cancer cell invasion." (PMID 34141705, 2021). "The expression of the integrin β3 subunit can induce the upregulation of MMP-2 and promote the invasive potential of breast cancer cells." (PMID 34946741, 2021). "Myricetin was also reported to suppress breast cancer metastasis through down-regulating the activity of the metalloproteinase matrix (MMP)-2/9." (PMID 34960117, 2021). "Eugenol treatment shows an anti-metastatic effect by reducing the invasion and migration of MDA-MB-231 breast cancer cells mostly by reducing the expression of MMP-2 and MMP-9." (PMID 34502165, 2021). "A previous study demonstrated that tangeretin inhibits metastasis in rat mammary carcinoma induced by 7,12-dimethylbenz (α) anthracene by downregulating MMP2, MMP9, and VEGF." (PMID 34335799, 2021). "In our collection of 183 breast cancer samples, abnormal hypermethylation was observed for CpGs in MMP2, MMP23B, MMP24, MMP25, and MMP28 promoter regions." (PMID 32397602, 2020). "Through microdialysis, they found increased endostatin and MMP-2 and MMP-9 levels in mice with breast cancer treated with tamoxifen, and inhibition of MMP-2 and MMP-9 resulted in a significant decrease in endostatin levels." (PMID 32669083, 2020). "PIPP-depleted breast cancer cells showed decreased levels of MMP2, which digests the basement membrane component collagen type IV to facilitate breast cancer cell invasion and metastasis." (PMID 33276499, 2020). "The ERα coregulators Amplified in breast cancer 1 (AIB1) and steroid receptor coactivator (SRC)-1 have been demonstrated to facilitate breast cancer metastasis through the induction of matrix metalloproteinase 2 (MMP2) and MMP9 and twist, respectively." (PMID 32759784, 2020). "Additional studies have found that a subset of the MMPs (e.g., MMP-2 and MMP-9) are upregulated in breast cancers and are associated with poor outcomes." (PMID 32384738, 2020). "Future studies are needed to examine how these multiple factors will influence MMP-2 levels in breast cancer patients who completed anthracycline-based chemotherapy." (PMID 32246106, 2020). "The disassociation of MMP‐2 with Hsp90 is induced by K69 acetylation on Hsp90 and results in the suppression of breast cancer invasion." (PMID 32180962, 2020). "MMP-2 production increased during the early phase of breast cancer, but also high levels of MMP-2 have been related to poor outcome in breast carcinomas." (PMID 33114046, 2020).
breast cancer (continued). "Previous authors have reported that MMP-2 was regulated via PI3K and NF-kB pathway in breast cancer and the inhibition of MMP-9 was associated with the inhibition of p-JNK." (PMID 33042020, 2020). "In basal-like TN breast cancer, CCL20 promotes bone metastasis by raising the secretion of MMP-2/9 and increasing the receptor activator of nuclear factors-kappa B (NF-κB) ligand/osteoprotegerin ratio in breast cancer and osteoblastic cells." (PMID 33489906, 2020). "Recent studies indicated that hypoxic mammary tumors secret lysyl oxidase (LOX) to recruit CD11b+ myeloid cell at metastasis sites and these cells produce MMP-2 to disport collagene IV in experimental breast cancer metastasis models." (PMID 33062602, 2020). "This microswimmer can be biodegraded by matrix metalloproteinase-2 (MMP-2) enzyme, an enzyme that is highly expressed in breast cancer." (PMID 32244653, 2020). "EGFR, COX2, MMP-1, and MMP-2 expressed in breast cancers jointly facilitate lung metastasis by promoting the angiogenesis, emancipating cancer cells into the circulation and breaking through lung capillaries." (PMID 33489906, 2020). "Enhancement of metastatic potency of breast cancer cells by neutrophils was demonstrated by increased MMP‐2 and MMP‐9 mRNA levels, as well as p‐p38 and p‐AKT protein levels only in the contact model." (PMID 32427405, 2020). "MMP14 and integrin αVβ3 complexes are capable of activating MMP2 activity with the assistance of TIMP2 in breast cancer and melanoma cells." (PMID 32352029, 2020). "The unusual nuclear localization of TFPI-2 also have been described in mammary cancer, and it was suggested that it is responsible for modulation of the expression of MMP-2 by interacting with the Ap2-α transcription factor." (PMID 32559232, 2020). "BTG1 overexpression was observed to inhibit migration and invasion of breast cancer cells with MMP-2 and -9 hypoexpression and E-cadherin hyperexpression." (PMID 33330092, 2020). "One of the specificities of breast cancer is that myoepithelial cells act as a protective barrier around the tumor cells and are able to decrease the secretion of MMP-2, MMP-9, and MT1-MMP." (PMID 32984031, 2020). "Kaempferol averts breast tumor infiltration and progression in MDA-MB-231 breast carcinoma cells by reducing MMP-2 and 9 expressions and subdual of AP-1 and MAPK signaling." (PMID 33520928, 2020). "Consistent with our findings, a previous study showed that overexpression of TES significantly inhibited breast cancer cell invasion and reduced breast cancer cell metastasis to the lung through blocking the secretion of matrix metallopeptidase-2 (MMP-2)." (PMID 30728082, 2019). "The upregulation of CD147 in MDA-MB-435 breast cancer cells promoted tumor growth, infiltration and metastasis in nude mice, and the expression of MMP-2 and MMP-9 increased in tumor cells." (PMID 31196010, 2019). "MMP-2 has been involved in the migration and invasion of ovarian, colorectal, bladder and breast cancer, where the increased activity and expression of these enzymes have been described." (PMID 31426440, 2019). "Densitometric analysis of the lytic bands showed that the activity values of pro-MMP-2 were significantly higher in MBP-1-ve breast cancer sera compared to MBP-1+ve and healthy sera." (PMID 31416219, 2019). "The majority of the breast cancer tissues were positive for the lytic activities corresponding to the latent and activated form of MMP-2 and MMP-9." (PMID 31416219, 2019). "Immunohistochemical analysis was performed using tissue samples of fibroadenoma and breast cancer to assess MMP-2 and MMP-9 antigen expression." (PMID 31839881, 2019). "An earlier study showed that EGR1 directly inhibits MMP2 in breast cancer cells by binding to its promoter." (PMID 30845713, 2019). "A. αVβ3 integrin interacts with MT1-MMP to promote MMP2 activation in breast cancer cell lines, but it also interacts with MMP2 to form a complex in blood vessels of melanoma tumors in vivo." (PMID 31052560, 2019).
breast cancer (continued). "Autocrine GH stimulates WNT4 expression in breast cancer cells, which, in turn, increases mesenchymal markers vimentin, MMP2, and MMP7, while inducing cell migration and suppressing apoptosis." (PMID 31939481, 2019). "Huaier has been reported to be able to inhibit the EMT process by suppressing the expressions of N-cadherin and MMP-2 in gastric cancer and breast cancer cell lines." (PMID 31391034, 2019). "Higher levels of MMP‐9 and MMP‐2 have been repeatedly described in the malignant tissues of the patients with infiltrative breast cancer and lymph node metastasis." (PMID 31264317, 2019). "Regarding the histological grade, the breast cancer group showed positive expression for MMP-2 in 13 (52%) moderately differentiated (histological grade II) tumors, 10 (40%) histological grade III tumors and 2 (8%) histological grade I tumors." (PMID 31839881, 2019). "In particular, the invasiveness of breast cancer is closely related with overexpression of MMP-2 and MMP-939." (PMID 31406126, 2019). "In situ zymography studies were conducted cryostat sections of A-673 (rhabdomyosarcoma), HT1080 (fibrosarcoma), and BT-20 (breast cancer) xenograft (CD-1 nude mice), showing high, weak and low MMP-2 and -9 activities, respectively." (PMID 31426440, 2019). "Intriguingly, extracellular HSP70 forms the activation complex with various co-chaperones, including HSP90α, Hop, and HSP40, which together promote the migration and invasion of the breast cancer cells via the enhanced activity of MMP2." (PMID 31878360, 2019). "Other evidences have established a positive correlation between H2O2 content and MMP2 activity in MCF-7 breast cancer cells also showing that CoQ10 application decreases H2O2 production leading to the inhibition of MMP2 activity." (PMID 30984333, 2019). "In cellular models of breast cancer, both MMP-2 and MMP-9, participate in invasion, metastasis and angiogenesis." (PMID 31554180, 2019). "Studies have showed that concentrations of MMP-2 and MMP-9 are increased in women with breast cancer, and are associated with an unfavorable prognosis." (PMID 31839881, 2019). "A large study including US Hispanic/Latina women tested associations between polymorphisms in MMP-1, MMP-2, MMP-3, and MMP-9 genes and breast cancer risk." (PMID 30781715, 2019). "Further, increased synthesis and activity of MMP-2 augment the biological aggressiveness of breast cancer." (PMID 31367263, 2019). "This binding stimulates downstream signaling that results in increased MMP-2 gene expression, which can enhance cell migration in breast carcinoma." (PMID 31182680, 2019). "The present investigation represents the continuation and upgrading of our previous studies, now focusing on the occurrence and intensity levels of MMP-2 and -9 and their proteomic correlations in a cohort of 80 breast cancer surgical tissues." (PMID 30060564, 2018). "Genetic ablation of host MMP-2 in mice, and hence also in bone-lining osteoblasts, significantly delayed the growth of bone metastatic breast cancer, with reduced levels of TGFβ indicated as a contributing mechanism." (PMID 29874869, 2018). "The potentially important role of matrix-degrading enzymes in breast cancer has been stated for many years, in particular in relation to the activities of MMP-2 and MMP-9." (PMID 30060564, 2018). "Further, low MMP-2 and MMP-9 mRNA levels are associated with better overall survival for breast cancer patients." (PMID 29874869, 2018). "MMP-2 plays a crucial role in the progression of breast cancer by degrading extracellular matrix (ECM) components." (PMID 30140603, 2018). "In this work, Maitake D-Fraction was shown to decrease the activity of MMP-2 and MMP-9 secreted by TNBC MDA-MB-231 cells, two MMPs clearly linked to breast cancer metastatic potential." (PMID 29805742, 2018). "In the context of breast cancer progression and bone metastasis, several MMPs have been shown to play important roles, and of these MMPs, MMP-2 has several noted roles." (PMID 29874869, 2018).